MYD88 (MYD88 innate immune signal transduction adaptor)
Diseases named in the same sentence as MYD88 in open-access papers (continued):
Sharing a sentence is not in itself a finding about the gene and the disease.
inflammation (continued). "The western blot results showed that TLR4/MyD88/Traf6 was elevated after METH treatment, suggesting that METH treatment induced liver inflammation, and antibiotics pretreatment can reverse this elevation." (PMID 34381368, 2021). "RAG-KO mice reconstituted with MyD88-KO lymphoid cells and sensitized with OVA/Alum also developed allergic eosinophilic inflammation as well as increased levels of total and OVA-specific IgE antibodies when compared to control groups." (PMID 28220116, 2017). "In conclusion, FD attenuates BLM‐induced pulmonary inflammation and fibrosis through suppressing the activation of NALP3 inflammasome and the IL‐1β/IL‐1R1/MyD88/NF‐κB signalling pathway." (PMID 27306439, 2016). "This study demonstrated that FD, attenuates BLM‐induced pulmonary inflammation and fibrosis in mice via inhibiting the activation of NALP3 inflammasome and the IL‐1β/IL‐1R1/MyD88/ NF‐κB pathway." (PMID 27306439, 2016). "Consistent with BML-111-induced downregulation of the TLR2/MyD88/NF-κB pathway, the OVA-induced airway inflammation was restrained, as shown by the reduced serum levels of IL-1β, IL-4 and IL-8, as well as BALF levels of IL-1β, IL-4, IL-8, OVA-IgE." (PMID 25760938, 2015). "Dexmedetomidine (10and 20 μg/kg) significantly decreased mortality and pulmonary inflammation of septic rats, as well as suppressed CLP-induced elevation ofTNF-α and IL-6 and inhibited TLR4/MyD88 expression and NF-κB activation." (PMID 23690665, 2013). "Poly(I:C) is a synthetic ligand for TLR3, the only MyD88-independent TLR, allowing isolation of the effect of MyD88 deletion on ventilator-augmentation of lung inflammation." (PMID 21092115, 2010). "Furthermore, FD inhibits BLM-induced lung inflammation and fibrosis in mice via the activation of the NALP3 inflammasome and inhibition of the IL-1β/IL-1R1/ MyD88/NF-κB pathway." (PMID 36834561, 2023). "GO-203 exacerbated TLR4/MyD88/NF-κB pathway activation in vivo, and NLRP3 inflammasome-mediated pyroptosis reduced in a mouse model of asthmatic neutrophil airway inflammation induced by OVA/LPS; these pathological changes were partially alleviated after TAK-242 application." (PMID 37880668, 2023). "On the other hand, HFD could up-regulate the levels of inflammatory factors in serum, indicating HFD-induced renal inflammation, suggesting that TLR4/MyD88-activated signaling is involved in HFD-induced renal injury." (PMID 36230117, 2022). "In addition to the classic TLRs/MyD88/NF-κB pathway, STING/IRF3/NLRP3 signaling is involved in the LPS-induced cardiac inflammation, apoptosis, and dysfunction." (PMID 35721566, 2022). "In addition, cigarette smoke-induced pulmonary inflammation is dependent on Toll-like receptor (TLR) 4/MyD88 and IL-1R1/MyD88 signaling." (PMID 25889448, 2015). "In addition, other danger signal receptors independently of STING or TLR9 may be activated leading to type I IFN/IFNAR-dependent pulmonary inflammation including MDA5/RIG-l, TLR4/MyD88, TLR7MyD88 or TLR8/MyD88,)." (PMID 31619733, 2019). "Thus, absence of a functional MyD88 pathway largely prevented ozone-induced lung inflammation." (PMID 29867931, 2018).
infectious disease (18 papers, 2007 to 2025). A disorder directly resulting from the presence and activity of a microbial, viral, or parasitic agent in humans. "Because of the critical role of MyD88 signaling, mice deficient in MyD88 have profoundly impaired innate immune responses and are susceptible to a wide range of infectious diseases." (PMID 22848400, 2012). "The findings were found align with previous report displaying that nsSNPs in conserved regions of immune regulatory proteins, such as MyD88 and IRAK4 disrupt protein stability and function, increasing susceptibility to infectious disease." (PMID 41231851, 2025). "The TLR/MyD88/NF-κB signaling pathway is a key pathway in the inflammatory response system of fish, and it is widely present in a wide range of fish tissue cells and is involved in the pathogenesis and regulation of inflammatory and infectious diseases." (PMID 41227537, 2025). "The activation of the TLR4/MyD88/NF-κB signaling pathway has been shown to promote the secretion of immune factors and enhance dendritic cell (DC) antigen presentation, playing a crucial role in combating infectious diseases." (PMID 39749332, 2024). "Besides, the protective role of AHCC® in infectious diseases seems to be related to its immunomodulatory properties by priming TLR-4 and TLR-2 and the associated TLR-4/MyD88 and NF-κB/MAPK signal transduction pathways." (PMID 31484389, 2019). "Therefore, TLR2/MyD88/NF-κB signaling pathway plays an important role in infectious diseases and inflammatory diseases, and inhibiting TLR2 could treat soft tissue infections by inhibiting inflammation and protecting tissues." (PMID 35222679, 2022). "MyD88-dependent and -independent pathways exhibit differences in TLR4-related infectious and non-infectious diseases." (PMID 39238498, 2024). "We also cannot rule out whether the MYD88-STING1 pathway is required for ACOD1-related inflammatory responses in other infectious diseases or tissue damage." (PMID 35769880, 2022).
metabolic disorders (15 papers, 2010 to 2025). "It has been well established that coupling between TLRs and MyD88 initiates innate immunity in several types of peripheral cells and is also involved in the hypothalamic inflammatory responses linked to metabolic disorders." (PMID 32560726, 2020). "The purpose of this study was to test the physiological role of MyD88 in the state of metabolic disease using MyD88-deficient mice." (PMID 20824098, 2010). "T cell-specific knockout of myeloid differentiation primary response 88 (MyD88) results in abnormal IgA antibody responses and an altered microbial gut community, leading to more severe inflammatory diseases, age-associated obesity, and metabolic disorders." (PMID 33679800, 2021). "Especially, MyD88 deficiency causes weight gain, impaired glucose homeostasis and increased expression of pro‐inflammatory cytokines, indicating that regulating MyD88 expression can be a potential approach to controlling metabolic disorders and inflammatory diseases." (PMID 33830560, 2021). "We show that targeting intestinal epithelial MyD88 confers protection or therapeutic effects against diet-induced metabolic disorders." (PMID 25476696, 2014). "As saturated fatty acids-induced activation of TLR4 is involved in enhancing metabolic disease, we expected that MyD88 would exacerbate metabolic disease." (PMID 20824098, 2010). "Finally, correlation analysis revealed a surprising finding that GC effectively targets the Akkermansia-TLR4/Myd88/NF-κB pathway axis to ameliorate glycolipid metabolism disorders." (PMID 38539827, 2024). "Before we determined whether HFD-induced metabolic disorder could be ameliorated by specific Myd88 KO in the astrocytes, we investigated the effect of astrocyte-specific Myd88 KO on energy metabolism under the STD feeding condition." (PMID 32560726, 2020). "So far, there are no human studies showing that host intestinal epithelial MyD88 controls gut microbiota composition and that this is associated with metabolic disorders." (PMID 25476696, 2014). "Thus, this set of experiments unequivocally showed that intestinal epithelial MyD88 is a primary sensor of the HFD-induced stresses that are able to induce various metabolic disorders." (PMID 25476696, 2014). "Connected with MyD88 and TLR signaling genes (TNF-α, IL-6, IL-12);Participates in metabolic disease(TGF-β1)." (PMID 39911236, 2024). "FO and PO exhibit similar protective effects on metabolic disorders and inflammation through inhibiting TLR4 signaling in a manner dependent on MyD88." (PMID 34168108, 2021). "Rodents with pharmacological inhibition and knockdown of TLR4 as well as neuronal deletion of the TLR adaptor molecule myeloid differentiation primary response 88 (MyD88) are protected from HFD-induced leptin resistance and metabolic disorders." (PMID 33741533, 2021). "In summary, the present study demonstrates that FO and PO have the similar protective effects on metabolic disorders and inflammation through inhibiting TLR4 signaling in a manner dependent on MyD88." (PMID 34168108, 2021). "Thus, in the present study, we focused on by possible functional role of myeloid differentiation factor 88 (MyD88), an essential adapter protein for TLR/interleukin (IL)-1 receptor signaling, in metabolic disease." (PMID 20824098, 2010).
cardiovascular diseases (10 papers, 2009 to 2025). "The involvement of NLRP3 MyD-88 and some DAMPs in ICIs-associated cardiovascular disease was seen." (PMID 36158826, 2022). "Clinical studies are required to elucidate the effects of ICIs on myocardial and vascular inflammation and confirms the role of NLRP3 and Myd88 in progression of ICIs-mediated cardiovascular diseases." (PMID 36158826, 2022). "While most of these studies were carried out in non-regenerative mammalian models, understanding the role of MyD88 in a regenerative system should provide insights into the pathogenesis of cardiovascular diseases and the development of new treatment approaches." (PMID 39271818, 2024). "The widespread involvement of these pathways in cardiovascular endurance is the basis for future mechanistic studies which may identify MyD88 as effective target for therapeutic intervention in cardiovascular diseases." (PMID 39247623, 2024). "All of these drugs showed varying levels of activity on TLR/MyD88 signalling, and have varying pharmacodynamic properties, therefore could be useful for specific forms of cardiovascular diseases (CVD) depending on the exact contributions of MyD88." (PMID 39247623, 2024). "While this pathway was initially characterized in innate cells, it has been found that MyD88 is broadly expressed across most cell types of the immune system and cardiovascular systems, often exerting distinct roles specific to certain cell types within cardiovascular disease contexts." (PMID 39247623, 2024). "In addition, a comprehensive understanding of the MyD88 pathway’s contribution to the regenerative response will determine whether targeting a molecule of the innate immune system could be considered as a treatment target to limit pathogenesis in cardiovascular diseases." (PMID 39271818, 2024).
lung (10 papers, 2013 to 2024). "It will also be important to determine whether blockade of both mTOR and MyD88 completely prevents development liver inflammation." (PMID 34630435, 2021). "Furthermore, these protective effects of RIPC against liver IR injury appear to be mediated by KATP through inhibiting HMGB1-induced TLR4/MyD88/NF-κB signaling." (PMID 31771292, 2019). "In our present study, we found that pigs with M. hyorhinis infection had evidence of lung inflammation, including significant interstitial infiltration of inflammatory cells and thickening of the alveolar walls, as well as the activation of the TLR4/MyD88/NF-κB p65 signaling pathway." (PMID 35699454, 2022).
hematological malignancies (7 papers, 2013 to 2023). "Although these mutations have all been linked to hematologic malignancies, MYD88 is of particular interest as it occurs in at least 35% of patients with PCNSL." (PMID 34729485, 2021). "Accumulation of mutations play a key role in the aging process, and it was shown that mutation of MAX is associated with hereditary pheochromocytoma, whereas mutation of MYD88 was found to be associated with many hematological malignancies." (PMID 26895224, 2016). "TLR activation by somatic MYD88 mutations and chronic inflammations has been implicated in a number of hematological malignancies." (PMID 25132836, 2014). "Inappropriate activation of TLRs due to the somatic acquisition of gain-of-function mutations in the TLR adaptor protein MYD88 has been implicated in many hematological malignancies." (PMID 25132836, 2014). "Constitutively, active NFκB signaling due to the aberrant activation of TLRs during chronic inflammation or by MYD88 mutation determines the poor clinical outcome of many hematological malignancies." (PMID 25132836, 2014). "The activation of the immune system is usually caused by direct contact between intestinal immune cells and microbial metabolites, which activates TLR4/MyD88/NF-kB signaling in B cells and the immune response, and promotes the progression of hematological malignancies." (PMID 37190210, 2023). "Recently the MYD88 mutation has been emerged as a hallmark of WM/LPL, implicating in its diagnosis, management, and treatment.1 patient with LPL was diagnosed with IgG4-associated disease 7 years after the diagnosis of hematological disease." (PMID 36172352, 2022).
liver (7 papers, 2016 to 2025). "The PPI networks identified 10 hub genes that were implicated in digestive tumour immunotherapy target TIM-3 (Myd88, Traf6, Irf7, Cdk4, Ccnd2, Mapkap1, Prr5, Mpp3, Serpinb6b and Pvrl3)." (PMID 38434966, 2024). "Our analysis of PPI networks identified 11 hub genes (Myd88, Traf6, Irf7, Cdk4, Ccnd2, Mapkap1, Prr5, Mpp3, Serpinb6b and Pvrl3) that were implicated in digestive tumours." (PMID 38434966, 2024). "After quinic acid treatment, the expression level of MyD88 protein and the phosphorylation level of NF-κB and IκB-α decreased significantly, indicating that quinic acid suppressed DSS-induced colon inflammation by inhibiting the activation of the MyD88/NF-κB signaling pathway." (PMID 40647020, 2025).
peripheral neuropathy (6 papers, 2017 to 2025). A disorder affecting the peripheral nervous system. "In a paclitaxel-induced peripheral neuropathy model, there was an increased in expression of Myd88 protein in CGRP positive neurons of DRG along with mechanical hyperalgesia." (PMID 32825453, 2020). "Consistently, intrathecal administration of MyD88 inhibitor suppresses pain of paclitaxel-induced peripheral neuropathy when applied 14 days after paclitaxel administration." (PMID 28359290, 2017). "TLR4/MyD88 has been reported to be involved in paclitaxel-induced peripheral neuropathy in rats." (PMID 31775332, 2019). "Therefore, TLR4/MyD88 signaling is involved in paclitaxel-induced peripheral neuropathy." (PMID 31775332, 2019). "Myeloid differentiation factor-88 adaptor protein (Myd88) mediates activation of Tlrs or interleukin 1 receptor (IL1-R) and leads to NF-κB activation in peripheral neuropathy and has been shown to be a therapeutic target for NP." (PMID 32825453, 2020).
kidney disease (5 papers, 2013 to 2025). "Previous studies have shown that TLR4 plays a role in inflammatory and fibrotic processes in renal diseases, which are usually associated with activation of the MyD88-NF-κB pathway." (PMID 32388684, 2020). "To explore this possibility further, we studied the progression of two models of kidney disease in mice deficient in TLR-2, TLR-4 and MyD88." (PMID 23844229, 2013). "The top-ranked item by betweenness centrality, not only established the linkage between TLR2 and kidney diseases but also confirmed that TLR2 might participate in ischemia-reperfusion via both MyD88-dependent and MyD88-independent pathways in the pathogenesis of acute ischemic kidney injury." (PMID 40584714, 2025).
neurodegenerative disease (4 papers, 2012 to 2024). A disorder of the central nervous system characterized by gradual and progressive loss of neural tissue and neurologic function. "The inhibitory effect of 152 was found to be regulated by the inactivation of the NF-κB, MAPK, and TLR4/MyD88 signaling pathways, indicating that 152 presented potential anti-inflammatory candidates for the treatment of neurodegenerative diseases." (PMID 39452841, 2024). "The inhibitory effect of 206 was found to be regulated by the inactivation of the NF-κB, MAPK, and TLR4/MyD88 signaling pathways, indicating that 206 presented potential anti-inflammatory candidates for the treatment of neurodegenerative diseases." (PMID 39452841, 2024). "The inhibitory effect of 163 was regulated by the inactivation of the NF-κB, MAPK, and TLR4/MyD88 signaling pathways, indicating that 163 is potential anti-inflammatory candidate for the treatment of neurodegenerative diseases." (PMID 39452841, 2024). "It has also been reported by others that TLR 2, 4, and 9 signaling modulates phacogytosis and clearance of neurotoxic amyloid deposition in neurodegenerative diseases, perhaps by MyD88 independent signaling pathways." (PMID 22363497, 2012). "Furthermore, another experimental study conducted on Male Wistar rats indicated that vitamin D has the potential to prevent or treat neurodegenerative diseases by suppressing the TLR4/MyD88/NF-κB pathway, which is known to play a crucial role in the development of myocardial inflammation." (PMID 38920563, 2024).
adenocarcinoma (3 papers, 2015 to 2023). A common cancer characterized by the presence of malignant glandular cells. "We also showed that MyD88 expression was significantly higher in the well- and moderately differentiated tumors than in the poorly differentiated tumors, and most of the intestinal-type adenocarcinoma are well-differentiated." (PMID 32477927, 2020).
cardiac disease (3 papers, 2022 to 2026). "It is reported that MyD88 plays a vital role in the development of heart disease." (PMID 35692080, 2022). "Among these genes are TGFβ1, IL10, and MYD88 which are known to participate in cardiac disease." (PMID 36248879, 2022).
neurologic disease (3 papers, 2024 to 2025). "EVs derived from the periodontopathogen Aggregatibacter actinomycetemcomitans can alleviate neurological diseases by downregulating the TLR4/MyD88 signaling pathway and reducing the expression of pro-inflammatory cytokines." (PMID 39472001, 2024).
retinopathy (3 papers, 2013 to 2020). "This demonstrates that MyD88 is upstream of many of the pro-inflammatory proteins that we and others have demonstrated are important for development of early stages of the retinopathy, and it controls the induction of those pro-inflammatory proteins." (PMID 23874797, 2013). "However, little has been done to investigate miR-146a and MyD88 in retinopathy-like conditions." (PMID 26997759, 2016).
intestinal bacterial infection (2 papers, 2017 to 2019). "We show that caspase-11 is required for IL-1β- and LPS-driven STAT1 activation in IECs, suggesting that caspase-11 facilitates crosstalk between MyD88 and STAT1 signalling pathways at the intestinal barrier, to promote anti-tumorigenic signalling during inflammation-associated intestinal disease." (PMID 30538296, 2019).
myopathy (2 papers, 2014 to 2023). A disease of the muscle in which the muscle fibers do not function properly. "Many studies clearly suggest that TLRs, acting through MyD88-dependent and/or independent mechanisms, induce pro-inflammatory signals for the development of myopathy in skeletal muscles." (PMID 24410812, 2014). "By activating the MyD88 signaling pathway and its downstream NF-κB pathway, TLR4 ultimately upregulates the strong pro-inflammatory factor IFN-γ and forms a pro-inflammatory myopathy environment." (PMID 36742332, 2023).
central nervous system diseases (1 paper, 2021). "The activation of the TLR4/MyD88 signaling pathway has been widely observed in central nervous system diseases, including AD." (PMID 34650664, 2021).
musculoskeletal disease (1 paper, 2018). "Thus, MyD88 may serve as a potential target for ES-62 in resetting baseline levels of HSCs, and OCPs, with this molecule providing the first example of a defined helminth ES product rewiring bone-remodeling progenitor populations in vivo to protect against the development of musculoskeletal disease." (PMID 29867986, 2018).
respiratory diseases (1 paper, 2021). "The discovery and development of pharmacological inhibitors of MyD88 signaling suggest MyD88 as a drug target to treat respiratory diseases, which may represent a significant therapeutic progress." (PMID 33834387, 2021).